MT-TT (mitochondrially encoded tRNA-Thr (ACN))
Synonyms: trnT; formerly MTTT; LIMM
Gene: Mitochondrial transfer RNA gene on chromosome MT (15,888 to 15,953, forward strand). Ensembl gene ENSG00000210195.
Gene Ontology:
Molecular function: triplet codon-amino acid adaptor activity
Biological process: translation
Gene-disease validity (ClinGen):
ClinGen rates the evidence that MT-TT causes each of these diseases.
mitochondrial disease (mitochondrial): Moderate.
Diseases named in the same sentence as MT-TT in open-access papers:
MT-TT is named in the same sentence as 1 disease in open-access papers, as found by Europe PMC text mining. Sharing a sentence is not in itself a finding about the gene and the disease.
MT-TT shares sentences with these, for which no sentence is quoted: infection (1 paper).